ADAM10 (ADAM metallopeptidase domain 10)
Diseases named in the same sentence as ADAM10 in open-access papers (continued):
Sharing a sentence is not in itself a finding about the gene and the disease.
Sepsis (15 papers, 2015 to 2026). Sepsis is defined as life-threatening organ dysfunction caused by a dysregulated host response to infection. "Spearman correlation analysis revealed a significant positive association between ADAM10 and VE-Cadherin in sepsis patients (rho = 0.421, p = 0.005)." (PMID 41596215, 2026). "Given the evidence suggesting that ADAM10 and miR-23b play pivotal roles in the pathogenesis of sepsis, we carried out this study to evaluate the association between ADAM10, miR-23b, and sepsis." (PMID 31780861, 2019). "A previous study concluded that rs653765 is a functional variant in the promoter region of ADAM10, while indicating the existence of a close association with the progression of sepsis." (PMID 30926762, 2019). "The aim of this study was to confirm the association between the ADAM10 promoter rs653765 G→A polymorphism and the progression of sepsis and to discover the underlying mechanism." (PMID 31387910, 2019). "Our recent preliminary study showed that the ADAM10 genetic polymorphism was clinically associated with the development of sepsis, and little is known about the underlying mechanism." (PMID 31387910, 2019). "ADAM10 expression levels were significantly increased in septic patients and animal models of sepsis and were markedly associated with disease severity and mortality." (PMID 31780861, 2019). "Two genetic variants in the promoter of ADAM10 were selected to analyze the potential association with the risk of sepsis." (PMID 25888255, 2015). "Next, we analyzed the genotype distribution of ADAM10 mRNA expression to investigate the possible relationship between these polymorphisms and the expression of the ADAM10 gene in severe sepsis patients." (PMID 25888255, 2015). "Future studies are warranted to validate whether ADAM10 directly mediates VE-Cadherin shedding in this setting and to test whether ADAM10 inhibition can mitigate sepsis risk in LVAD patients." (PMID 41596215, 2026). "After incorporating ADAM10 into the VE-Cadherin prediction model, the model’s predictive performance improved across all five time points, further supporting its role in the pathophysiology and risk stratification of postoperative sepsis in LVAD patients." (PMID 41596215, 2026). "The pairing of these human studies with mechanistic analyses in tractable animal models may in turn provide a foundation for clinical risk stratification in sepsis and facilitate therapeutic targeting of ADAM10." (PMID 37788087, 2023). "Specifically, S. aureus secretes alpha-toxin, which is a major virulence factor that mediates pathogenic functions in sepsis by interacting with the widely expressed host cell receptor, a disintegrin and metalloproteinase domain-containing protein 10 (ADAM10), on platelets and leukocytes." (PMID 36750777, 2023). "It is plausible that combination therapy achieving ADAM10 inhibition and antiplatelet activity may be particularly effective in the management of sepsis caused by those pathogens that elicit complex microvascular injury through an ADAM10-dependent mechanism." (PMID 37788087, 2023). "We considered whether ADAM10 may be an upstream molecular pathway in sepsis pathogenesis, especially given the observation that an ADAM10 promoter polymorphism modulates sepsis severity." (PMID 37788087, 2023). "Association between ADAM10 polymorphisms and the susceptibility and progression of sepsis." (PMID 31387910, 2019). "The underlying mechanism of miR-23b in the regulation of ADAM10 expression and sepsis-induced inflammatory responses may provide new opportunities for the development of potential therapeutic interventions against the disease." (PMID 31780861, 2019). "Our study confirmed that the rs653765 G→A SNP contributes to sepsis progression in a large sample size of sepsis patients recruited from three representative areas of China, which authenticated the susceptibility gene of ADAM10 and added a new mutation site for sepsis." (PMID 31387910, 2019).
Sepsis (continued). "However, the underlying mechanisms of miR-23b in the regulation of ADAM10 and sepsis remain uncharacterized." (PMID 31780861, 2019). "Our data initially indicated the ADAM10 rs653765 polymorphism was associated with the development of severe sepsis; the risk CC genotype could functionally affect the expression level of ADAM10 mRNA and was accompanied by the up-regulation of its substrates." (PMID 25888255, 2015). "Consequently, in the present study, we investigated the association of these two functional SNPs, rs514049 and rs653765, which are located in the promoter region of the ADAM10 gene, with the risk of sepsis." (PMID 25888255, 2015). "In the present study, for the first time, we demonstrated that individuals carrying the functional variant rs653765 in the promoter region of ADAM10 may exhibit susceptibility to the development of sepsis." (PMID 25888255, 2015). "A recent study reported that ADAM10 induces the loss of endothelial barrier function in septic mice and that the severity of cellular injury and sepsis is mitigated by ADAM10 inhibition, which led us to investigate the relationship between ADAM10 and sepsis." (PMID 25888255, 2015). "In addition, ADAM10 influences the production of inflammatory cytokines; its excessive activation has been linked to systemic inflammatory responses and disruption of the vascular endothelial barrier following sepsis." (PMID 41596215, 2026). "Moreover, mice harboring endothelial ADAM10 deletion were protected against Pseudomonas aeruginosa and Streptococcus pneumoniae sepsis, yet maintained susceptibility to lethal infection with other human sepsis pathogens." (PMID 37788087, 2023). "Emerging evidence suggests that the biological effects of ADAM10 activity are tightly linked to the development and progression of inflammatory response via various cellular processes, which may represent key regulatory mechanisms regarding sepsis progression." (PMID 31387910, 2019). "Although genetic variants of the A disintegrin and metalloproteinase 10 (ADAM10) gene have been shown to be associated with susceptibility to several inflammatory-related diseases, to date little is known about the clinical relationship in the development of sepsis." (PMID 25888255, 2015). "The present case-control study examined 440 sepsis patients and 450 healthy controls to determine whether the promoter variations of ADAM10 (rs653765 and rs514049) are associated with susceptibility to sepsis and whether these two functional SNPs influence ADAM10 expression in sepsis patients." (PMID 25888255, 2015). "A significant positive correlation between VE-cadherin and ADAM10 was detected only among sepsis patients." (PMID 41596215, 2026). "Across all sampling points, plasma VE-cadherin and ADAM10 levels were significantly higher in the sepsis group relative to the non-sepsis group." (PMID 41596215, 2026). "In our study; however, the primary aim was to evaluate the utility of perioperative and early postoperative VE-Cadherin and ADAM10 levels in predicting later sepsis." (PMID 41596215, 2026). "We also observed significantly higher plasma ADAM10 levels across all time points and a strong positive correlation between circulating ADAM10 and VE-Cadherin, observed exclusively in patients with sepsis." (PMID 41596215, 2026). "During sepsis, endothelial ADAM10 is activated; it cleaves VE-cadherin, disrupts interendothelial junctions, and increases vascular permeability." (PMID 41280722, 2025). "In mice with induced sepsis, miR-23b-5p was reduced, coupled with an elevation in ADAM10 and other MMPs." (PMID 40565140, 2025). "Here, we define a pathogen-specific role of ADAM10 in sepsis, allowing us to begin to shift the paradigm from a single sepsis pathway toward an understanding of pathogen-defined pathways as the primary inciting event in cellular and tissue dysregulation." (PMID 37788087, 2023).
Sepsis (continued). "Our findings provide the rationale for pathogen-specific analysis of the ADAM10 rs653765G promoter SNP in individuals presenting with sepsis." (PMID 37788087, 2023). "Additional mechanistic studies of the role of ADAM10 in sepsis and the contribution of SNP-based regulation of ADAM10 expression in disease are needed." (PMID 37788087, 2023). "The independent effects of genetic alteration of ADAM10 expression and ADAM10 inhibition on sepsis mortality and vascular injury highlight the potential use of small-molecule inhibitors as a novel host-targeted approach to modify disease." (PMID 37788087, 2023). "To circumvent the impact of ADAM10 deletion on vascular development, we utilized an endothelium-specific inducible knockout system to assess the role of the metalloprotease in sepsis." (PMID 37788087, 2023). "Together, these studies provide the first in vivo evidence to our knowledge that the role of endothelial ADAM10 in the pathophysiology of sepsis extends beyond that of the known Hla-ADAM10 complex, exhibiting pathogen specificity." (PMID 37788087, 2023). "In this study, PBMCs and serum were extracted from blood samples of 30 sepsis patients and 30 healthy controls to evaluate the expression of miR-23b and ADAM10 and the inflammatory response in sepsis patients." (PMID 31780861, 2019). "This evidence suggests the potential crucial role of EGR1 in regulating ADAM10 expression in sepsis patients." (PMID 31387910, 2019). "Several lines of evidence have demonstrated that ADAM10 plays significant roles in the pathological mechanism of sepsis." (PMID 31780861, 2019). "The expression level of EGR1 in sepsis patients was evaluated to further characterize the clinical association between EGR1 and ADAM10." (PMID 31387910, 2019). "Our study reports the mechanism of the association between rs653765 and the risk of sepsis progression and provides the EGR1/ADAM10 pathway involving the regulation of nosogenesis of sepsis based on the clinical genetic evidence." (PMID 31387910, 2019). "In this study, our results indicated an increase in ADAM10 expression in sepsis patients and THP-1 cells upon LPS treatment." (PMID 31780861, 2019). "Previous studies have demonstrated pivotal roles of disintegrin and metalloproteinase 10 (ADAM10) in the pathogenesis of sepsis." (PMID 31780861, 2019). "The enhanced expression of ADAM10 in septic mice and patients with sepsis was observed to be closely correlated with disease severity and mortality." (PMID 31780861, 2019). "We found that the sepsis patients displayed a significantly higher ADAM10 mRNA expression level than the healthy controls (P <0.01)." (PMID 25888255, 2015). "When the sepsis patients were divided into subgroups, we observed that ADAM10 expression was significantly higher in the patients with severe sepsis or septic shock than in the patients with sepsis (both P <0.01)." (PMID 25888255, 2015). "The difference in the ADAM10 mRNA expression level between each genotype was further analyzed in the sepsis patients." (PMID 25888255, 2015). "Furthermore, we observed a significant positive correlation between ADAM10 and VE-Cadherin exclusively in the sepsis cohort." (PMID 41596215, 2026). "We aim to evaluate the efficacy of VE-Cadherin and ADAM10 for predicting sepsis in LVAD patients." (PMID 41596215, 2026). "Interestingly, ADAM10 deletion in a sepsis mouse model with Pseudomonas aeruginosa and Streptococcus pneumoniae showed a reduction in mortality; an effect that was not seen with Group B Streptococcus or Candida albicans." (PMID 41408425, 2026). "While prior studies have been limited to analysis of sepsis severity across cohorts of patients with sepsis, a refinement of clinical investigation to include ADAM10 SNP typing for pathogen-specific analyses may be highly informative." (PMID 37788087, 2023).
Sepsis (continued). "Together, these data suggest that specific bacterial cytotoxins may either initiate or amplify ADAM10-dependent endothelial injury, resulting in platelet aggregation and microvascular thrombosis in the pathogenesis of sepsis." (PMID 37788087, 2023). "Additional studies will be needed to reveal whether the effects of this polymorphism in vivo stem solely from endothelial ADAM10 function or also depend on other cell types in which ADAM10 may contribute to sepsis pathogenesis." (PMID 37788087, 2023). "The ability of diverse bacterial cytotoxins to elicit endothelial injury, together with the central role of ADAM10 in endothelial homeostasis, led us to hypothesize that ADAM10 is a central mediator of sepsis-induced endothelial dysfunction." (PMID 37788087, 2023). "The use of active-site ADAM10 inhibitors such as GI254023X has shown promising preclinical results to improve sepsis; however, the evaluation of these agents in humans remains limited by nonspecific inhibitory effects on ADAM17 and unfavorable toxicities with chronic use." (PMID 37788087, 2023). "As ADAM10 is essential for endothelial development and homeostasis, we examined whether other major human sepsis pathogens also rely on ADAM10-dependent pathways in pathogenesis." (PMID 37788087, 2023). "In the context of sepsis, Hla decreases platelet–endothelial cell adhesion through ADAM10-mediated cleavage of platelet glycoprotein VI (GPVI), compromising hemostasis but simultaneously promoting neutrophil inflammatory signaling by augmenting the platelet-neutrophil interaction." (PMID 37788087, 2023). "Our study not only sheds light on the specific role of the Hla-ADAM10 interaction in endothelial injury in S. aureus sepsis, but, perhaps more importantly, illustrates that utilization of ADAM10 differentiates molecular pathways of disease among common human sepsis pathogens." (PMID 37788087, 2023). "Several limitations of mouse modeling systems may obscure a complete understanding of the role of ADAM10 in pathogen-specific outcomes in sepsis." (PMID 37788087, 2023). "This evidence indicates that ADAM10 may serve as an indicator of sepsis severity and that the blockade of ADAM10 may be a promising therapeutic target for sepsis." (PMID 31780861, 2019). "Our findings may advance our understanding of the role of miR-23b and ADAM10 in modulating the biological processes of inflammatory responses in sepsis." (PMID 31780861, 2019). "The molecular regulatory mechanism of miR-23b in ADAM10 expression and sepsis-induced inflammatory consequences may provide potential therapeutic targets for sepsis." (PMID 31780861, 2019). "In addition, the specific antagonist or genomic deletion of ADAM10 contributes to a significant decrease in septic response and endothelial barrier disruption and confers a protective benefit against sepsis to mice." (PMID 31780861, 2019). "Thus, our data suggest new insight into the novel mechanism of the EGR1/ADAM10 pathway in the regulation of sepsis progression." (PMID 31387910, 2019). "These lines of evidence indicate that the blockade of ADAM10 may be a promising therapeutic target for sepsis." (PMID 31780861, 2019). "In the present study, we confirmed that a functional variant acts as an important genetic factor that confers the progression of sepsis in a large sample size and in multiple centers and revealed that the variants modulate the EGR1/ADAM10 pathway and influence the severity of sepsis." (PMID 31387910, 2019). "Moreover, in vitro functional experiments were also conducted to identify the role of miR-23b in regulating inflammatory responses by targeting ADAM10 following sepsis." (PMID 31780861, 2019). "In light of the crucial role of the EGR1/ADAM10 signaling pathway in the sample of sepsis patients and in vitro models that confirmed this, we evaluated whether EGR1 could serve as a therapeutic target for sepsis." (PMID 31387910, 2019).
Sepsis (continued). "The molecular regulatory mechanism of miR-23b in ADAM10 expression and sepsis-induced inflammatory consequences may provide new opportunities for the development of potential therapeutic interventions against the disease." (PMID 31780861, 2019). "Studies have demonstrated that the expression levels of ADAM10 increased in various murine models of sepsis, which could reflect the organ dysfunction and mortality seen in sepsis." (PMID 31387910, 2019). "The direct binding of the EGR1 to the ADAM10 promoter is modified, affecting the transcription and translation of the ADAM10 gene, resulting in enhanced inflammatory responses and ultimately stimulating the progression of sepsis in vitro and in vivo." (PMID 31387910, 2019). "AT contributes to multiple aspects of S. aureus pathogenesis during bacteremia and sepsis, including stimulating a hyperinflammatory response characteristic of sepsis and activating ADAM10-mediated cleavage of endothelial tight junctions, leading to a loss in vascular integrity (14, –, 16)." (PMID 27353753, 2016). "Moreover, the rs653765 CC genotype in severe sepsis showed a higher ADAM10 level compared to healthy groups, and the rs653765 CC polymorphism had a strong impact on the production of the ADAM10 substrates CX3CL1, IL-6R and TNF-α." (PMID 25888255, 2015). "This evidence suggests that ADAM10 may play a vital role in the pathogenesis of directly inflammatory-related diseases, such as sepsis." (PMID 25888255, 2015). "Rs653765 SNP is a functional SNP in severe sepsis, and the CC genotype may increase the ADAM10 mRNA expression level, thereby influencing the levels of ADAM10 substrates, which may ultimately contribute to the risk for the development of sepsis." (PMID 25888255, 2015). "ADAM10 may be a promising therapeutic target for the prevention and treatment of sepsis." (PMID 41596215, 2026). "ADAM10 may play a crucial role in the development of sepsis in LVAD patients." (PMID 41596215, 2026). "Upon infection of WT and VE-Cad ADAM10–/– mice with these pathogens, VE-Cad ADAM10–/– mice were protected against lethal sepsis caused by P. aeruginosa and S. pneumoniae, but not sepsis due to GBS or C. albicans." (PMID 37788087, 2023). "Second, our studies lend support for further investigation of the role of antiplatelet agents in the management of sepsis, raising the possibility that this class of drugs may benefit individuals infected with pathogens that rely on endothelial ADAM10 for induction of microvascular thrombosis." (PMID 37788087, 2023). "Hence, ADAM10 could act as a downstream mediator of miR-23b involved in the regulation of sepsis-induced inflammatory responses and apoptosis in human THP-1 monocytes." (PMID 31780861, 2019). "Alternatively, ADAM10 may ultimately influence the risk of severe sepsis via other inflammation- or non-inflammation-related pathways aside from those which we examined." (PMID 25888255, 2015). "However, we did not observe any association between the ADAM10 polymorphisms and the levels of pro-inflammatory cytokines in the severe sepsis patients." (PMID 25888255, 2015). "To determine whether this functional ADAM10 SNP ultimately influences the expression of pro-inflammatory cytokines, we investigated the expression levels of IL-1ß and IL-6 in PBMCs from patients with severe sepsis." (PMID 25888255, 2015). "Moreover, to investigate the effect of these ADMAM10 variants on the inflammation process, we analyzed the possible associations between these polymorphisms and the expression levels of downstream substrates of ADAM10 and pro-inflammatory cytokines in sepsis patients." (PMID 25888255, 2015). "Moreover, among the patients with severe sepsis, the rs653765 CC genotype carriers exhibited a higher ADAM10 expression level than the rs653765 CT/TT carriers, suggesting than this SNP may be functional." (PMID 25888255, 2015).